ZCRB1 (zinc finger CCHC-type and RNA binding motif containing 1)
Synonyms: MADP-1; MADP1; RBM36; ZCCHC19; SNRNP31
Tractability: PROTAC: ubiquitination databases record sites on it.
Gene: Protein-coding gene on chromosome 12 (42,312,086 to 42,326,257, reverse strand). Ensembl gene ENSG00000139168.
Subcellular location: Nucleus, nucleoplasm
Pathways (Reactome):
Disease: Replication of the SARS-CoV-1 genome; Replication of the SARS-CoV-2 genome
Metabolism of RNA: mRNA Splicing - Minor Pathway
Gene Ontology:
Molecular function: protein binding; RNA binding; nucleic acid binding; zinc ion binding
Biological process: mRNA splicing, via spliceosome; RNA splicing
Cellular component: U11/U12 snRNP; U12-type spliceosomal complex; cytosol; nucleoplasm
Genetic constraint (gnomAD): Loss-of-function variants: 17 observed, 24.14 expected, observed/expected ratio (o/e) 0.7, 90% interval 0.48 to 1.06. The upper end of that interval is the gene's LOEUF score, 1.06, which puts it in group 4 of 6, group 1 being the genes least tolerant of losing a copy. Missense variants: 179 observed, 239.46 expected, observed/expected ratio (o/e) 0.75, 90% interval 0.66 to 0.85. Synonymous variants: 72 observed, 78.13 expected, observed/expected ratio (o/e) 0.92, 90% interval 0.76 to 1.12.
Homologues: Orthologues: chimpanzee ZCRB1 (100% identical), macaque ZCRB1 (99% identical), dog ZCRB1 (99% identical), pig ZCRB1 (98% identical), rat Zcrb1 (95% identical), mouse Zcrb1 (95% identical), guinea pig ZCRB1 (93% identical), tropical clawed frog zcrb1 (78% identical), zebrafish zcrb1 (78% identical). Paralogues in human: RBMX2 (29% identical), CSTF2 (25% identical), CSTF2T (24% identical), U2AF2 (18% identical), UHMK1 (12% identical).
Diseases named in the same sentence as ZCRB1 in open-access papers:
ZCRB1 is named in the same sentence as 14 diseases in open-access papers, as found by Europe PMC text mining. Sharing a sentence is not in itself a finding about the gene and the disease. The quoted sentences say what the papers report.
breast carcinoma (1 paper, 2021). "For example, ZCRB1 was overexpressed in lymphoma, and ADH1C in cervical cancer and esophageal cancer, and YTHDC2 in breast cancer, gastric cancer, head and neck cancer, myeloma, and sarcoma." (PMID 34178026, 2021).
COVID-19 (1 paper, 2021). A disease caused by infection with severe acute respiratory syndrome coronavirus 2. "COVID-19 has infected plenty of people around the world, and ZCRB1 high expression may impact patients’ prognosis." (PMID 34178026, 2021).
glioma (1 paper, 2022). A benign or malignant brain and spinal cord tumor that arises from glial cells (astrocytes, oligodendrocytes, ependymal cells). "Moreover, Kaplan–Meier survival curves and ROC curves indicate that ZCRB1 may be a useful prognostic and diagnostic biomarker for glioma patients." (PMID 35538499, 2022). "In the GEPIA database, low expression of ZCRB1 was correlated with worse overall survival and disease-free survival of glioma patients." (PMID 35538499, 2022).
lung adenocarcinoma (1 paper, 2021). A carcinoma that arises from the lung and is characterized by the presence of malignant glandular epithelial cells. "Through genome-wide analysis of lung adenocarcinoma and healthy subjects, it was found that ZCRB1 may encode viral receptors." (PMID 34178026, 2021).
ovarian carcinoma (1 paper, 2025). A malignant neoplasm originating from the surface ovarian epithelium. "Similarly, regulators of RNA processing and splicing such as TCEA1, SF3B6, ZCRB1, PNO1, and DCAF13 were overexpressed, indicating dysregulation of mRNA metabolism and splicing fidelity in ovarian cancer." (PMID 41228302, 2025).
cancer (4 papers, 2021 to 2026). A tumor composed of atypical neoplastic, often pleomorphic cells that invade other tissues. "In addition, previous studies have shown that VAMP2 and ZCRB1 are expressed in cancers and promote tumor progression." (PMID 41596398, 2026). "However, the function of ZCRB1 was rarely reported in cancer, only in two studies." (PMID 34178026, 2021). "In our study, we found that most cancer driver genes are specifically expressed in tumor tissue, and we constructed a four-mRNA prognostic signature (ETV5, EZH2, PABPC1, ZCRB1) that has higher predictive power than other clinical features." (PMID 34335239, 2021).
tumor (4 papers, 2021 to 2026). "As a tumor suppressor gene, ZCRB1 phosphorylates JMJD5 to regulate aerobic glycolysis in GBM through the cyclic RNA HEATR5B." (PMID 36909185, 2023). "Considering the knockout of ZCRB1 had the strongest tumor-inhibiting effect in the proliferation experiment, specifically, we selected ZCRB1 as the target to determine its effect on proliferation, invasion, migration, and colony formation." (PMID 36909185, 2023). "As a result, in vitro experiments suggest that ZCRB1 expression is closely related to malignant behavior in tumor cells, and it could become a new therapeutic target for copper homeostasis and cuproptosis." (PMID 36909185, 2023). "In addition, transwell invasion and migration experiments confirmed that ZCRB1 downregulation significantly reduced tumor cell invasion and migration." (PMID 36909185, 2023). "Finally, nude mouse xenograft models were used to clarify the in vivo tumor-suppressive effects of ZCRB1, circHEATR5B, and HEATR5B-881aa." (PMID 35538499, 2022). "CDKN2A, GEMIN2, DLAT, and ZCRB1 were expressed at higher levels in tumors than in normal tissues, while the expression of KLF9 in tumor tissue was lower." (PMID 36909185, 2023).
ZCRB1 also shares sentences with these, for which no sentence is quoted: cervical cancer (1 paper); esophageal cancer (1); gastric cancer (1); head and neck cancer (1); lymphoma (1); myeloma (1); sarcoma (1).